CXCL5 (C-X-C motif chemokine ligand 5)
Diseases named in the same sentence as CXCL5 in open-access papers (continued):
Sharing a sentence is not in itself a finding about the gene and the disease.
tumor (continued). "Meanwhile, CXCL5 expression was significantly related to tumor progression and survival time." (PMID 37393391, 2023). "Similarly, in hepatocellular carcinoma, the upregulation of CXCL5 promotes tumor growth, lung metastasis, and intra-tumoral neutrophil infiltration, whereas its downregulation reduces tumor growth, metastasis, and TAN infiltration." (PMID 37444436, 2023). "In addition, CXCL5 and CXCR2 ligand-receptor interaction drive infiltration of tumor-associated macrophages (TAMs) and myeloid-derived suppressor cells (MDSCs), promoting cancer metastasis in prostate cancer." (PMID 37698493, 2023). "This may indicate low usefulness of CXCL5 in the detection of benign lesions, but on the other hand, it can be a useful parameter when detecting tumor initiation." (PMID 37848726, 2023). "Immunoassay for chemokines secreted by ACKR1+ tumor cells showed a decrease in CXCL5 and CXCL8, and chemokine detection suggested the chemokines were bound by ACKR1 and internalized or immobilized on the cell surface rather than removed from the tumor microenvironment." (PMID 37006247, 2023). "Except for CXCR6, all cytokines/cytokine receptors were shown to operate in the spine, with CX3CL1, CX3CR1, IL10, CCL2, CXCL12, and CXCR4 mediating bone marrow colonization, CXCL5 and TGFβ promoting tumor cell proliferation, and TGFβ additionally driving bone remodeling." (PMID 36835198, 2023). "SPP1+ TAMs exhibit enriched gene signatures involved in Wnt signaling pathway and support tumor growth while CXCL5+ TAMs enriched in angiogenesis pathways, indicating that TAMs might promote tumor vasculature to facilitate tumor metastasis." (PMID 37936694, 2023). "In addition, the deletion of Col 1 in α-SMA+ myCAFs leads to CXCL5 upregulation in cancer cells, which is associated with recruitment of MDSCs and suppression of CD8+ T cells, suggesting that myCAFs slow tumour progression in PDAC." (PMID 36284087, 2022). "CXCL5 can be produced by tumor cells, macrophages, and neutrophils." (PMID 35505821, 2022). "In addition, the levels of CXCL5 were significantly higher in the lymph node metastatic tissue of head and neck squamous cell carcinomas than those in the primary tumor area." (PMID 35702353, 2022). "In addition, NDRG3 also up-regulate the expression of angiogenic chemokine 43 (CXCL1, CXCL3 and CXCL5), enhance the expression of Angiogen-44, thereby ultimately promoting tumor progression." (PMID 36619553, 2022). "Notably, CXCL5 was reported to promote tumor cell migration and invasion in PCa, especially in relation to bone metastasis." (PMID 35853880, 2022). "The expression of CXCL5 is upregulated in multiple malignant tumor types." (PMID 35504887, 2022). "CXCL5 is highly expressed in hepatocellular and prostate cancers, as well as cholangiocarcinoma and esophageal squamous carcinoma, promoting tumor growth and metastasis as a key protein involved in the regulatory of cancer immunity enriched in the migrasome." (PMID 36405728, 2022). "This study manifested that miR-145-3p may be a tumor suppressor in EC, and miR-145-3p/CXCL5 axis restrained the malignant progression of EC." (PMID 35936390, 2022). "Moreover, immunohistochemistry was carried out on tumor samples to examine the correlation between CXCL5 expression and disease prognosis." (PMID 36151545, 2022). "In addition, they found that CXCL5 also increased microvessel density in a subcutaneous xenograft tumor model in nude mice by overexpression treatment of CXCL5." (PMID 35770088, 2022). "To determine whether Cxcl5 is a major player downstream of Foxf2, we investigated whether suppressing Cxcl5 can attenuate or ablate stromal Foxf2-mediated tumor suppressive effect." (PMID 36369237, 2022).
tumor (continued). "A series of experiments and treatment of cancer cells with the small molecular inhibitor LY294002 as an inhibitor of PI3K/AKT signaling indicated that CXCL5 secreted by CAFs binds to the CXCR2 receptor at the surface of tumor cells and induces PD-L1 expression at these cells via this pathway." (PMID 36275750, 2022). "CXCL5 could regulate tumor progression in an autocrine or paracrine manner in a vast number of cancers." (PMID 33458757, 2021). "Similarly, Sorafenib treatment recruits tumor neutrophil infiltration in animal models as well as HCC patients by inducing the CXCL5 expression in tumor cells via the hypoxia-inducible factor 1-alpha (HIF1α)/nuclear factor-κB (NF-κB) pathway." (PMID 34830850, 2021). "In NSCLC models, CXCL-5 depletion was seen to inhibit tumour angiogenesis." (PMID 34336101, 2021). "Neutrophils could be recruited into ICC tumour through CXCL5 to promote tumour metastasis and recurrence." (PMID 33833794, 2021). "In response to interferons, macrophages are polarized and activated into pro-inflammatory classical M1 type that produces cytokines, such as interferon-γ (IFN-γ), tumor necrosis factor-α (TNF-α), IL-23, IL-12, CCL5, CXCL9, CXCL10, and CXCL5 and help destroy tumor cells via activating Th1 cells." (PMID 33925575, 2021). "Up to now, there are many reports about the mechanism of CXCL5 promoting tumor progression." (PMID 33869023, 2021). "Knocking down DDR1 reduced the level of CXCL5 in the primary tumor and plasma." (PMID 34237033, 2021). "Based on ONCOMINE, GEPIA, and cBioPortal databases, the expression levels of CXCL5 were correlated with different tumor stages and high transcriptional levels of CXCL5 may exhibit poorer overall survival in patients with HCC." (PMID 33869023, 2021). "Interestingly, correlation analysis showed a significant positive correlation between circCTNNA1 and CXCL5 expression in CRC tumor tissues." (PMID 33640021, 2021). "In addition, we also discovered that CXCL5 was markedly upregulated in CRC tumor tissues compared to adjacent normal tissues at the mRNA and protein levels." (PMID 33640021, 2021). "Infiltrative intertumoral neutrophils recruited by CXCL5 could promote tumor metastasis and the recurrence of intrahepatic cholangiocarcinoma." (PMID 34868992, 2021). "CXCL5 overexpression has been observed in several malignancies, including osteosarcoma, glioma, and lung, bladder, liver, prostate and colorectal cancers, demonstrating its roles in tumor carcinogenesis." (PMID 32201508, 2020). "Platelets secrete CXCL5 and CXCL7, contact with tumor cells cause recruitment of granulocytes (CD11b+MMP9+Ly6G+) to tumor cells in lung to form early metastatic niches directly helping in tumor cell seeding and development of lung metastases." (PMID 33414786, 2020). "It was also found that CXCL5 attracted MDSCs to the primary tumor site to induce EMT in vivo." (PMID 32596152, 2020). "We showed that CXCL5 exhibited a strong chemotactic activity to neutrophils and enhanced the expression of several factors that have been reported to be responsible for their pro-tumor roles in neutrophils." (PMID 32632106, 2020). "Besides that, TANs can also secret TGF-β2 to trigger miR-301-3p-related stem cell characteristics in the oncogenic hepatocytes, which will then secrete a higher level of CXCL5 and recruit more neutrophils to infiltrate the tumour and generate a pro-tumour TME." (PMID 33114183, 2020).
tumor (continued). "Likewise, CXCL5 is overexpressed in ccRCC, and based on its involvement in angiogenesis, tumor growth, and metastasis has been deemed an important biomarker and a critical adjunct antiangiogenic therapy target." (PMID 32028264, 2020). "The univariate analysis showed that high CXCL5 expression in tumor tissues (p=0.001), the T stage (p=0.004), the N stage (p<0.001), the differentiation status (p=0.001), and high level of CA19-9 (p=0.001) and CA242 (p=0.008) were significantly associated with poor OS." (PMID 32201508, 2020). "High expression of CXCL5 was associated with lymphatic metastasis and tumor differentiation but had no relevance with age, gender, tumor size, and invasion depth." (PMID 32632106, 2020). "Since CXCL5 activates neutrophils and induces the expression of pro-tumor factors in neutrophils, we determined whether CXCL5-activated neutrophils represented a pro-tumor phenotype." (PMID 32632106, 2020). "However, consistent with the results from primary tumours, we detected significantly elevated levels of Cxcl5 in JL BM mononuclear cell samples compared with LD samples." (PMID 32581213, 2020). "Overexpression of CXCL5 is found in various cancers and promotes tumor growth and metastasis." (PMID 32632106, 2020). "CXCL5 mediated inflammation and tumor growth in bone, it may serve as a potential target for cancer therapeutics." (PMID 32346605, 2020). "CXCL5 expression in tumor tissue was elevated compared to that in normal pancreatic tissue." (PMID 32201508, 2020). "Indeed, CXCL5 acts as potent chemotactic stimulus for neutrophils in vitro and induces tumoral neutrophil infiltration in vivo through PI3K/Akt and ERK1/2 activation." (PMID 32784743, 2020). "In another report, the ELR+ CXC chemokine CXCL5 was shown to up-regulate BC cell proliferation in an ex vivo tumor-bone co-culture system that assessed the switch from dormancy to colonization through stimulation of tumor cell growth." (PMID 33585241, 2020). "In addition, the CXCR2/CXCL5 pair has been shown to enhance tumour progression by increasing the formation, recruitment and suppressive activity of MDSCs." (PMID 31010082, 2019). "Thus, in the present study, we confirmed that CXCL5 promotes tumor angiogenesis both in vitro and in vivo." (PMID 30792394, 2019). "The influence of CXCL5 on tumor angiogenesis in vivo was also evaluated using Matrigel plugs." (PMID 30792394, 2019). "Furthermore, to determine the role of CXCL5 in tumor angiogenesis, the tumor nodules were stained for CXCL5 and the microvessel marker CD31." (PMID 30792394, 2019). "In addition, CXCL5 also enhanced tumor angiogenesis in vivo, which was confirmed by a subcutaneous xenotransplanted tumor model and Matrigel plugs in nude mice." (PMID 30792394, 2019). "CXCL5 is a chemokine that can recruit not only neutrophils, but also CXCR2+ myeloid-derived suppressor cells (MDSCs) and CXCR2+ monocytes that can be precursors of tumor-associated macrophages (TAMs)." (PMID 31080803, 2019). "However, very little information is available regarding the effects of CXCL5 on tumor angiogenesis in CRC." (PMID 30792394, 2019). "Furthermore, our results also confirmed that CXCL5 overexpression enhanced tumor volume and tumor angiogenesis in an in vivo model." (PMID 30792394, 2019). "Therefore, our data suggest treating TGF‐β/CXCL5‐positive patients directly against CXCL5, to circumvent tumor‐promoting functions of inflammation." (PMID 30014484, 2019). "In addition, CXCL5 mediates several cellular functions, including neutrophil trafficking and tumor migration and invasion." (PMID 30792394, 2019). "Taken together, our data could be a strong evidence that CXCL5 has a tumor-promoting effect in CRC as a positive regulator of tumor angiogenesis both in vitro and in vivo." (PMID 30792394, 2019).
tumor (continued). "Hence, this combination can not only achieve a cancer-specific sensitisation to TRAIL-induced apoptosis, but also concurrently reduces the levels of potentially tumour-progressive cytokines such as CXCL5/ENA-78 and IL-6." (PMID 31010082, 2019). "In mice, tumor formation of transplanted HCC cells relied on CXCL5 expression." (PMID 30014484, 2019). "In addition, because only three studies respectively were included to evaluate the association between CXCL5 expression levels with DFS, PFS and RFS, more studies are necessary to explore the relationship between CXCL5 with tumor progression." (PMID 29743818, 2018). "CXCL1, CXCL2, and CXCL5 promoted LLC tumor growth with an increase in concentration." (PMID 29541408, 2018). "We also demonstrated that CXCL5 was primarily expressed in the tumor cell cytoplasm and cell membranes, which may indicate that the CXCL5 was predominantly produced by cancer epithelial cells instead of fibroblasts in the tumor mesenchyme." (PMID 28356111, 2017). "Although the function of CXCL5/CXCR2 on tumor metastasis is confirmed in vivo." (PMID 28356111, 2017). "By counterstaining the fibroblasts, we further found that, although CXCL5 staining was observed in the tumor mesenchyme, CXCL5 was primarily expressed in the tumor lesions rather than the fibroblasts, which were visualized with the fibroblast marker α-smooth muscle actin (αSMA)." (PMID 28356111, 2017). "In transgenic KPC mice of PDAC, high levels of CXCL5 in the tumor stroma were detected." (PMID 29379802, 2017). "At the same time, the Ma S group found that the CXCL5 production of tumor cells could be induced by IL-17A, and the infiltration of MDSCs in tumor sites was mediated by CXCL5/CXCR2." (PMID 28002798, 2017). "Furthermore, we also revealed that CXCL5 secreted by tumor cells was able to promote CRC migration through ERK/Elk-1/Snail-mediated EMT (Epithelial mesenchymal transition) and invasion via the AKT/GSK3β/β-catenin/MMP7 pathway in a CXCR2-dependent manner." (PMID 28356111, 2017). "Tumor upregulated chemokines included the followings: CXCL5 (138 fold increase); CCL25 (70 fold increase); CXCL11 (26 fold increase); CXCL6 (20 fold increase); CXCL1 and CXCL10 (11 fold increase); CXCL3 (8 fold increase); and CXCL9, CXCL2, and CCL3L1 (6 fold increase)." (PMID 29088818, 2017). "In accordance with our study, other researchers have also identified CXCL5 as an important mediator of tumor-derived angiogenesis, and blockade of CXCL5 may be a critical adjunct antiangiogenic therapy against cancer." (PMID 27848972, 2016). "It was also reported that loss of TGF-β signaling promoted CXCL1 and CXCL5 secretion, which increased migration of CD11b+ Gr-1+ MDSC to the tumor tissues, and played indirect roles in increasing the number of T helper 17 (Th17) cells which have a pro-tumorigenic effect." (PMID 27136535, 2016). "In deed, over-expression of CXCL5 increased tumor metastatic capacity." (PMID 25788272, 2015). "Immunohistochemical stain of xenograft tumor tissues confirmed strong ectopic expression of CXCL5." (PMID 25788272, 2015). "The average tumor weight were increased from 187mg to 735mg by CXCL5." (PMID 25788272, 2015). "Given the potential function of CXCL5 as a pro-angiogenic factor, together with its role to promote tumor cell growth and motility, high circulating levels of CXCL5 could potentially act to promote tumorigenic progression in concert with local factors." (PMID 25999952, 2015). "Furthermore, high expression of CXCL5 by the tumor cells leads us to believe that this is the main factor attracting G-MDSC to the primary tumor." (PMID 22331989, 2012). "CXCL5 is the main chemokine attracting MDSC to the primary tumor." (PMID 21980263, 2011).
tumor (continued). "Nanostring data from BRD4 inhibitor–treated tumors also revealed decreased tumor expression of chemokines important for MDSC recruitment to tumors including CXCL5, CXCL3, and CCL2, suggesting that the reduced intratumoral MDSC levels could be caused by impaired MDSC migration into the TME." (PMID 40762981, 2025). "However, there was no direct evidence to support that PSA levels were correlated with CXCL5 in the tissues or sera of clinical patients, which may be due to the divergent multi-tumor microenvironments that modulate them." (PMID 39765818, 2024). "CXCL5 induces neutrophilic tumor inflammation and may negatively affect the cancer immune-cycle." (PMID 39235457, 2024). "However, it also promotes MDSC chemotaxis through tumor‐derived CXCL5 in an AMP‐dependent manner." (PMID 37867243, 2023). "Besides, CXCL5 secreted by renal clear cell cancer cell can form a positive feedback that induces the transformation from normal to tumor-related fibroblast to facilitate tumor growth." (PMID 37393391, 2023). "However, CXCL12 and CXCL5 inhibit T cell migration into the tumor, and the array of chemokine receptors present on T cells may not match the tumor chemokine signatures, resulting in poor migration to the tumor site." (PMID 35008832, 2021). "Notably, the culture supernatant from tumor tissues which contained a high concentration of CXCL5 also recapitulated these effects which could be abolished by CXCL5 neutralizing antibody." (PMID 32632106, 2020). "In addition, serum CXCL5 concentrations were higher in patients with advanced GC in comparison to those with benign tumors, which may suggest a potential role of CXCL5 in GC progression." (PMID 33182840, 2020). "The combination treatment caused increased secretion of CCL2, CCL21, CXCL1, CXCL2, CXCL5, CXCL9 and CXCL16, whereas the levels of CCL11, CCL17, CCL19, CCL22, CCL25, CCL27 and CX3CL1, which are associated with protumourigenic effects, were decreased in the tumours." (PMID 33014356, 2020). "Interestingly, CXCL5, a chemokine known for its role in promoting the recruitment of MDSCs and TAMs towards tumor sites and its receptor CXCR2 in addition to the Tregs transcription factor FOXP3 were among the highly differentially expressed between the XRT group and XRT + GLZ group." (PMID 31015520, 2019). "Also unlike hematological malignancies that are easy to be targeted and reached by CAR-T cells, some of chemokines such as CXCL1 23, CXCL12, and CXCL5 24, 25 secreted by solid tumors prevent T cells from trafficking toward and infiltrating into the tumor lesions." (PMID 31754328, 2019). "Inflammatory CC (CCL2, CCL3, CCL5) and CXC (CXCL1, CXCL2, CXCL5, CXCL6, and CXCL8) chemokines recruit at the tumor site CCR2+ monocytes and CXCR2+ neutrophils that differentiate into tumor associated macrophages (TAMs) and tumor associated neutrophils (TANs), exerting pro- or anti-tumoral role." (PMID 30894861, 2019). "Together, these data indicate that CXCL5 may promote tumor angiogenesis in CRC." (PMID 30792394, 2019). "The mechanisms underlying the role of CXCL5 in tumor angiogenesis have not been fully defined." (PMID 30792394, 2019). "Therefore, we may speculate that CXCL5 might have different prognostic roles in different tumor stage and larger-scale, multicenter studies including all stage patients are needed to verify our hypothesis." (PMID 29743818, 2018). "Moreover, gel-liquid approach has enabled cell migration studies in response to specific cytokines such as tumour cell intravasation (i.e., migration towards blood vessels) under TNFα exposure or tumour cell extravasation (i.e., migration from blood vessels) under chemokine CXCL5." (PMID 30214484, 2018).